PLIN2 (perilipin 2)
Diseases named in the same sentence as PLIN2 in open-access papers (continued):
Sharing a sentence is not in itself a finding about the gene and the disease.
tumor (continued). "We further analyzed the relationship between the expression of PLIN2 in tumor center and invasive tumor front with distinct clinicopathological variables, including sex, age, TNM, T stage, N stage, and differentiation." (PMID 35372038, 2022). "The results showed that in the tumor center, patients with high PLIN2 expression had a shorter OS (p = 0.0028), MFS (p = 0.0285), and DFS (p = 0.0066)." (PMID 35372038, 2022). "The results demonstrated that PLIN2 was significantly associated with TNM and T stage in tumor center." (PMID 35372038, 2022). "Our recent studies revealed that CHKα2 can act as a protein kinase to phosphorylate PLIN2/3 and initiate lipid droplet lipolysis for tumor growth." (PMID 35463311, 2022). "Taken together, these data indicated that PLIN2+CD68+TAMs were involved in tumor immune escape, which promoted the poor prognosis of patients." (PMID 35372038, 2022). "Consistently, our results showed that the high expression of PLIN2 in the tumor center was related to advanced TNM stage, which featured as more infiltration of CD68+TAMs." (PMID 35372038, 2022). "Despite a great number of reports which highlighted the accumulation of PLIN2 in tumor progression, few studies have investigated the role of PLIN2 in tumor resistance to ICI." (PMID 35372038, 2022). "Following the concept of precision medicine, assessing Plin2 levels will allow for the stratification of tumor responsiveness to specific mitosis‐targeting drugs, including future Trip13 inhibitors as well as clinically established drugs such as paclitaxel." (PMID 36031387, 2022). "Consistently, the results in TIMER showed that the expression of PLIN2 was positively correlated with macrophages, DCs, and tumor-infiltrating lymphocytes (TILs) in HNSCC." (PMID 35372038, 2022). "Both in the tumor center and invasive tumor front, the expression of PLIN2 in OSCC sections had a cytoplasmic and membranous expression and mostly granular staining pattern." (PMID 35372038, 2022). "In the invasive tumor front, the high expression of PLIN2 showed a shorter OS (p = 0.0314) and MFS (p = 0.0022), but there was no statistical difference in DFS (p = 0.0536)." (PMID 35372038, 2022). "Numerous types of tumor exhibit a high PLIN2 level, but its tumorigenic or tumor-suppressive role has been in debate." (PMID 35372038, 2022). "Future research is needed to unravel the role of PLIN2 in tumor progression through immunomodulation." (PMID 35372038, 2022). "Previous studies have suggested the relationship between PLIN2 or TAMs and tumor pathological parameters." (PMID 35372038, 2022). "Upregulated genes included VEGFA, NDUFA4L2, NNMT2, and PLIN2, all previously shown to be involved in tumor development and progression 36,37." (PMID 36180422, 2022). "HIF‐2α‐mediated expression of PLIN2 can help derive the lipid storage required for ER homeostasis and contribute to tumor growth and pharmacologic resistance to ER stress." (PMID 34766135, 2021). "In this analysis, it is possible to observe a remarkable difference between the PLIN2 staining pattern in tumor tissue, which displays a considerably higher accumulation of PLIN2, and that in paired adjacent normal tissue." (PMID 30782775, 2019). "We discovered that blockade of DGAT1 not only reduced LD density and PLIN2, but it also had potent anti-tumor activities by suppressing tumor growth both in vitro and in vivo." (PMID 30816200, 2019). "Each PLIN protein exhibits individual expression pattern during tumorigenesis, for example PLIN2 expression correlates with tumor cell proliferation." (PMID 29295482, 2017). "The mean expression of PLIN2 mRNA in tumor tissue was 22678 (range 279-159128), in normal renal parenchyma 2855 (range 911-25707) with significant difference (p<0.0001)." (PMID 28404922, 2017). "In addition, the results of PLIN2 staining showed that high expression of PLIN2 was detected in tumor metastasis sites in lung tissues." (PMID 39875372, 2025).
tumor (continued). "Furthermore, we found that there was a small, but significant reduction in Perilipin 2 staining intensity on the TA muscle sections of KPC tumor-bearing Xbp1mKO mice compared with corresponding Xbp1fl/fl mice." (PMID 40655023, 2025). "To further characterize the correlation between PLIN2 and tumor dormancy, we also detected the expression level of dormancy-related marker p27 in SACC tumor tissues by IHC and found that the level of PLIN2 in SACC tissues was negatively related to the level of p27." (PMID 41408408, 2025). "Finally, a PLIN2‐targeting liposome is designed to efficiently suppress ascites production and tumor metastasis." (PMID 39921309, 2025). "Therefore, we subcutaneously injected SACC-LM cells overexpressing PLIN2 into mice, until the primary tumor reached approximately 500 mm3." (PMID 41408408, 2025). "However, in MGC samples, proliferative cells were widely present (yellow arrows) and PLIN2 expression was undetectable in most tumor cells (yellow arrows)." (PMID 39955307, 2025). "In the subcutaneous xenograft mouse model, we observed that the tumor volume and weight in the PLIN2 overexpression group were greater than those in the control group, whereas the tumor volume and weight in the CD36 inhibitor group was smaller than that in the PLIN2 overexpression group." (PMID 40640171, 2025). "PLIN2, a protein on the surface of lipids droplets, was proved to be over-expressed in ccRCC patients’ samples and was shown to promote lipids storage, tumor progression and tumor proliferation in ccRCC xenografts." (PMID 40933888, 2025). "Moreover, we investigated the level of PLIN2 in paraffin sections of 48 SACC tumor tissues and 10 NSG tissues samples using IHC staining." (PMID 41408408, 2025). "Next, a tumor recurrence model was established to investigate whether PLIN2-mediated autophagy promotes the recurrence of SACC." (PMID 41408408, 2025). "Moreover, PLIN2 mediated lipid storage promotes tumor proliferation and survival via maintaining the ER integrity during elevated protein synthesis in ccRCC." (PMID 36831657, 2023). "Moreover, high PLIN2 levels in the invasive tumor front were related to a shorter MFS in patients with OSCC, and it was positively correlated with infiltrating CD8+T cell exhaustion." (PMID 35372038, 2022). "PLIN2 was mainly expressed in tumor-infiltrating immunocytes (TIIs) of OSCC." (PMID 35372038, 2022). "Similar to the PLIN2 staining of tumor tissue, signals corresponded to LD membranes." (PMID 35834072, 2022). "The results indicated that a high expression of PLIN2 might promote tumor immune escape by upregulating immune checkpoint molecules." (PMID 35372038, 2022). "Thus, assessment of Plin2 levels enables the stratification of tumor responsiveness to mitosis‐targeting drugs, including clinically approved paclitaxel and Trip13 inhibitors currently under development." (PMID 36031387, 2022). "Similarly, in the tumor center and invasive tumor front, high expression of PLIN2 tended to develop postoperative disease." (PMID 35372038, 2022). "Therefore, PLIN2 exerts both tumorigenic and tumor suppressive roles during tumor development in a tumor content-dependent manner." (PMID 35372038, 2022). "Moreover, patients with a high PLIN2 level in immune cells had a higher TNM stage and were susceptible to postoperative metastasis, but the escalated PLIN2 level in invasive tumor front independently predicted shorter metastasis-free survival." (PMID 35372038, 2022). "PLIN2 positive cells were present in a highly variable amount in all tumor samples." (PMID 35834072, 2022). "An increased expression of HIF‐2α in tumor cells may lead to enhanced expression of the LD coat protein gene PLIN2." (PMID 34766135, 2021). "Other in vitro studies have demonstrated that increased levels of PLIN2 are present in different types of tumor, suggesting that PLIN2 may play an important role in tumorigenesis." (PMID 33735111, 2021).
tumor (continued). "The finding that PLIN2 expression in the primary tumor correlates with a worse prognosis suggests that at least in a subset of patients, pre-existing alterations in lipid metabolism could correlate with disease progression." (PMID 31905780, 2019). "Therefore, targeting PLIN2 for autophagy inhibition as an adjunct to the treatment of SACC may effectively kill dormant tumor cells, prevent SACC recurrence and improve the survival rate of patients with SACC." (PMID 41408408, 2025). "However, the expression pattern of PLIN2 in the tumor parenchyma and the mechanism of cancer promotion are unknown." (PMID 40640171, 2025). "In addition, the overall survival and metastasis free survival were significantly poorer in OSCC patients with high PLIN2 expression (P < 0.05), indicating that PLIN2 might promote tumor progression and predict poor prognosis in OSCC patients." (PMID 39875372, 2025). "Thus, HIF-2α mediated PLIN2 overexpression promotes tumor proliferation and survival." (PMID 36831657, 2023). "Furthermore, HIF-2α knockdown reduces tumor growth in ccRCC xenografts which could be partially restored by exogenous PLIN2 expression." (PMID 36831657, 2023). "The results suggested that PLIN2+CD68+TAMs may represent the tumor development degree in OSCC." (PMID 35372038, 2022). "IL1RAPL2 belongs to the interleukin-1 receptor (IL-1R) family, PLIN2 encodes perilipin 2 (also called adipophilin or adipose differentiation-related protein), SMAD3 plays an important role in regulating glucose energy homeostasis, and TSC1 is a critical tumour suppressor in mTOR pathway." (PMID 35328822, 2022). "Finally, analysis of lipid storage markers showed an increased expression of perilipin 2 (PLIN2) and hypoxia inducible lipid droplet-associated (HILPDA), and reduced levels of carnitine palmitoyltransferase 1A (CPT1A) mRNA in tumor specimens compared to normal kidney." (PMID 33322148, 2020). "Moreover, at a higher magnification, we observed that the punctate PLIN2 staining in the normal tissue (top) localizes at infiltrating cells such as macrophages, whereas the great majority of PLIN2 staining in tumor tissue localizes specifically at the cancerous epithelial cells (bottom)." (PMID 30782775, 2019). "By analyzing the correlation between PLIN2 levels and clinicopathological factors, the results showed that PLIN2 was significantly correlated with SACC pathological grade and tumor recurrence." (PMID 41408408, 2025). "Mechanistically, it is demonstrated that PLIN2 boosts HIF1α/SPP1 signaling in macrophages, thereby exerting pro‐tumor functions." (PMID 39921309, 2025). "In conclusion, our study identified PLIN2 as a key prognostic biomarker in CRC and revealed its dual role in promoting tumor progression." (PMID 40640171, 2025). "In summary, our data provide compelling evidence for the crucial role of CAFs in SACC dormancy, showing that PLIN2 carried by CAFs-EVs regulates LD autophagy in dormant SACC cells, thereby contributing to tumor recurrence and metastasis." (PMID 41408408, 2025). "PLIN2 facilitates macrophage polarization toward the M2 phenotype and activates the CD36-dependent EMT pathway in CRC cells, thereby enhancing tumor aggressiveness." (PMID 40640171, 2025). "In HCC cells exposed to energy stress, PFKL undergoes phosphorylation and interacts with Perilipin 2 (PLIN2) to promote lipid droplet–mitochondria tethering, which facilitates lipolysis and β‐oxidation, supporting tumor proliferation and survival." (PMID 41476787, 2025). "Functional experiments demonstrated that PLIN2 gene overexpression promoted the proliferation, migration and invasion of CRC cells and significantly facilitated tumor growth in vivo." (PMID 40640171, 2025). "Itch-mediated ubiquitination of PLIN2/PLIN5 regulates LD protein turnover, influencing tumor metabolic adaptation." (PMID 40370434, 2025).
tumor (continued). "To detect the expression pattern of PLIN2 mRNA in SACC and NSG tissues, we collected ten pairs of fresh SACC tumor tissues and corresponding adjacent tissues, and extracted total RNA for qRT–PCR verification." (PMID 41408408, 2025). "Tumor cells also manipulate phospholipid remodeling (LPCAT1) and lipid droplet formation (PLIN2) to evade immune detection and sustain growth under metabolic stress." (PMID 40076502, 2025). "We determined mRNA expression profiles of PLIN1, PLIN2, PLIN3, PLIN4, and PLIN5 in a panel of OC cell lines and tumor tissue, using RT‐PCR." (PMID 41041279, 2025). "Considering the well-accepted role of EMT in tumor metastasis, we detected the expression of EMT-related markers in OSCC cells after overexpression/knockdown of PLIN2 by RT-PCR and WB." (PMID 39875372, 2025). "In our informatics analysis based on public databases, PLIN3 was highly expressed in HCC tumor tissues, and positively correlated with the tumor grade and stage of HCC patients, while the expression pattern of PLIN2 was completely opposite." (PMID 37464334, 2023). "Thus, we speculated that PLIN2 might inhibit immune cell function to promote tumor metastasis." (PMID 35372038, 2022). "Tumor Immune Estimation Resource (TIMER), cBioPortal databases, and IHC analysis were used to investigate the relationship between PLIN2 and OSCC immune microenvironment." (PMID 35372038, 2022). "This was further confirmed by significantly increased gene expression of lipid droplet marker perilipin 2 and lipid transporter CD36 in tumor cells exposed to adipocytes both in the absence and presence of Atglistatin." (PMID 27588494, 2016). "In tumor cells and in leukocytes T2R38 was co-localized with perilipin-2, which is an established marker for lipid droplets." (PMID 26862855, 2016). "Our findings suggest that targeting PLIN2 and autophagy inhibition as part of primary SACC treatment may effectively eliminate dormant tumor cells and prevent SACC recurrence." (PMID 41408408, 2025). "Therefore, our data indicated that PLIN2 promoted the reactivation of local residual dormant SACC cells after primary tumor treatment by upregulating autophagy, ultimately leading to tumor recurrence." (PMID 41408408, 2025). "Importantly, to validate the efficacy of PLIN2‐targeting liposomes in vivo, we constructed a murine OC model by injecting ID8 tumor cells into the peritoneal cavity." (PMID 39921309, 2025). "Furthermore, a significant association was found between elevated levels of DGAT1, DGAT2, PLIN2, PLIN3, and TG and malignancy, especially in advanced tumor stages, underscoring their promise as therapeutic targets in OC." (PMID 41041279, 2025). "The results showed that sex, age, TNM, T stage, differentiation, and PLIN2 in the tumor center had no obvious prognostic value for OS and MFS." (PMID 35372038, 2022). "The first goal of our study was to analyze the incidence of LDs (via p-phenylenediamine staining and assessing the LD coating PLIN1, PLIN2, PLIN3) and size of LDs (via transmission electron microscopy) in canine OS tumor specimens derived from patients after surgery or necropsy." (PMID 35834072, 2022). "Immunofluorescence for PLIN1 showed no signal within the tumor, whereas PLIN2 positive cells were seen adjacent and within the necrotic region and PLIN3 was restricted to the necrosis surrounding area." (PMID 35834072, 2022). "PLIN2 knockdown activates UPR signaling and attenuates tumor growth in clear-cell renal carcinoma." (PMID 29295482, 2017). "FBOX2, ACSL4 and PLIN2 showed strong expression in all six tumour samples but weak or no expression in non-tumour tissues." (PMID 28378759, 2017). "In contrast, DPEP1, HADH, PLIN2, SCD5, SLC44A4, and UGT8 may function to suppress tumor growth via the regulation of immune cells with antitumor activity such as resting memory CD4 T cells, resting NK cells, M2 macrophages, resting and activated DCs, and resting mast cells." (PMID 38090559, 2023).
tumor (continued). "Moreover, the expression of PLIN2 in invasive tumor front was an independent prognostic indicator of MFS, not OS." (PMID 35372038, 2022). "Moreover, urinary levels of AQP1 and PLIN2 were observed to be correlated with the tumour size and stage but not with grade." (PMID 26482227, 2015). "The results demonstrated that the mRNA levels of PLIN1/PLIN4/PLIN5 were not correlated with tumor recurrence status, while PLIN2 and PLIN3 were correlated with tumor recurrence status." (PMID 37189627, 2023). "However, the expression pattern of PLIN2 in CRC tumor parenchyma and tumor microenvironment and its molecular mechanism in CRC are not clear." (PMID 40640171, 2025). "Tumor markers with high sensitivity and specificity have not yet been validated for ccRCC screening, but some candidate molecules have been recently proposed, such as aquaporin 1 (AQP1) and perilipin 2 (PLIN2)." (PMID 37370817, 2023).